MET (MET proto-oncogene, receptor tyrosine kinase)
Diseases named in the same sentence as MET in open-access papers (continued):
Sharing a sentence is not in itself a finding about the gene and the disease.
tumor (continued). "The result illustrates that data points are scattered across the entire chart area, indicating that the amount of MET immunoreactivity is either constant across the cancer (uniform negative or positive staining) or differs between the tumor center and periphery (variable staining)." (PMID 26909606, 2016). "Recent studies have documented localization of some tumor-related genes, such as CDK6, BRAF, and c-MET at the upstream/downstream domain of miR-183-96-182 cluster, suggesting that these genes might be regulated to process similar functions of tumor-related molecules." (PMID 27081087, 2016). "There were no changes in c-MET phosphorylation in tumor tissue." (PMID 26742633, 2016). "We suggest that defining MET positivity as IHC staining in 25% of tumor cells is not stringent enough to establish true MET overexpression, and could lead to negative results in clinical trials." (PMID 27013592, 2016). "Specifically, the phosphorylation of c-MET, a heterodimeric transmembrane receptor, has in this study been found to be significantly decreased after 20 min of ischemia in normal tissue, whereas no change has been detected in tumor tissues." (PMID 26742633, 2016). "There were no significant changes in the phosphorylation of the c-MET isoform in tumor tissue." (PMID 26742633, 2016). "In contrast, MET signaling might not be involved in tumor growth in this model, since the phosphorylation level of MET was relatively low in A549-Luc-BM1 cells, and since TAS-115 barely suppressed A549-Luc-BM1 cell proliferation in vitro." (PMID 27736957, 2016). "MET amplification was only detected in metastatic/recurrent tumors but not the primary tumor tissue, suggesting that MET amplification might be more common in treatment-refractory tumors than in primary untreated tumors." (PMID 27581465, 2016). "Although a more clinically-relevant analysis of tumor/host crosstalk requires the use of orthotopic models, we suggest that for GBM patients in clinical trials, the immune reactions of individual patients might help identify vulnerability to MET inhibitors." (PMID 26381735, 2015). "In addition, this tumor had focal amplification of HMGA2 and MET genes." (PMID 26275293, 2015). "Furthermore, only one hHGF negative mouse of 5 injected with MET-T1010I expressing tumor cells developed a tumor and none of the MET-WT or MET-Y1253D cohorts developed tumors indicating that human HGF is required for optimal tumor development in SCID mice." (PMID 25605252, 2015). "Combining sorafenib and tivantinib, a VEGF inhibitor and a selective MET inhibitor, may provide synergistic or additive anti-tumor activity overcoming the resistance to sorafenib without causing possible off-target side effects of an unselective agent." (PMID 25294187, 2015). "Finally, we compared MET- and EGFR-expression within these tumor tissues to investigate, whether a correlation exists between both biomarkers." (PMID 26215852, 2015). "Recent analysis of previously unreported results has shown that crizotinib produced either disease stabilization or tumor response in patients with NSCLC and high MET amplification, suggesting that crizotinib may be a potential agent for the treatment of MET-amplified NSCLC." (PMID 28536405, 2015). "Furthermore, levels of MET and HER3 were quantitated in the 34 baseline tumor specimens collected." (PMID 26439803, 2015). "Additionally, recent research has demonstrated that VEGF could negatively regulate HGF/c-MET axis through a MET/VEGFR2 heterocomplex, therefore suppress tumor invasion." (PMID 26620439, 2015). "The dual inhibition of MET and VEGFR2 by cabozantinib may account for its activity in additional tumor types such as metastatic castration-resistant prostate cancer, renal cell carcinoma, and hepatocellular carcinoma, in which it is currently in phase III clinical trials." (PMID 25388653, 2014). "The mutation may compromise the negative feedback function of the MET pathway, and thus lead to tumor growth." (PMID 25119929, 2014).
tumor (continued). "However, we observed that Crizotinib did not decrease expression of p-c-MET in tumor tissue using immunostaining and western blotting." (PMID 25193856, 2014). "In later stages of tumor growth, tumor access may be limited by the restored blood-brain barrier, although it is likely that this block is not 100%, given that phospho-c-MET is still significantly reduced in treated tumors." (PMID 23484006, 2013). "Therefore, while MET amplification may be a rare event in localized CRC, it is more common in advanced tumor stages." (PMID 24005867, 2013). "However, increased expression of MET was detected by qPCR in tumor samples from CRPC patients compared to metastatic non-castrate PCa patients." (PMID 24205338, 2013). "The antibodies generated fell into three categories: 1) agonist antibodies as previously reported; 2) a series of antibodies that only bind the c-MET precursor and therefore may be tumor-specific; and, 3) bivalent antibodies that induce c-MET degradation and inhibit tumor growth." (PMID 22511956, 2012). "Besides tumor formation upon injection in mice, c-METhigh cells isolated from these primary tumor xenografts were also capable of forming spheroids in vitro whereas c-METlow or c-MET- cells were not." (PMID 24213498, 2012). "This is consistent with the analysis of MET expression by conventional RT–PCR, which shows expression of MET mRNA in all 19 tumours with no known translocation: quiescent satellite cells normally express MET, the receptor for hepatocyte growth factor, prior to entering S-phase." (PMID 12865925, 2003). "For instance, dual blockade of EGFR and MET may overcome MET-amplified or MET-driven resistance, whereas combining EGFR-TKIs with PD-1/PD-L1 inhibitors can potentially counteract TKI-induced upregulation of PD-L1 and the induction of an immunosuppressive tumor microenvironment (TME)." (PMID 41472727, 2025). "Furthermore, EGFRm circulating tumor DNA (ct-DNA) clearance on treatment (around cycle 3/4) predicted longer PFS in patients with detectable baseline ctDNA, while nearly half of the patients developed acquired resistance, mainly involving MET, EGFR, and KRAS alterations." (PMID 40725428, 2025). "Consequently, the dual specificity of c-MET BsAbs toward both c-MET on tumor cells and immune cell receptors like CD3 or PD-1 facilitates the mobilization and activation of immune cells to eliminate c-MET-overexpressing tumor cells, thereby amplifying the effectiveness of cancer immunotherapy." (PMID 39664377, 2024). "The crosstalk between MET amplification and the Wnt/β‐catenin signaling pathway was further investigated through gene expression and survival analysis in a cohort of 66 EGFR mutated NSCLC patients without any non‐tumor related diseases, which were carefully selected from the GEO database." (PMID 38867713, 2024). "Interestingly, EGFR was found to interact with c-MET and phosphorylate PARP-Y907 in the HCC cells that have high EGFR and c-MET expression, and simultaneous inhibition of both EGFR and c-MET significantly increases the anti-tumor activity of PARPi in such HCC cells." (PMID 36284291, 2022). "Since the goal of this investigation was to evaluate whether the soluble MET ectodomain is a relevant biomarker for overall tumor burden and malignant potential (details below), no further functional analyses were performed concerning the origin of these fragments." (PMID 35326642, 2022). "Intratumoral heterogeneity, reflected by the presence of a MET amplification in only one morphological region of the tumor but not the other, poses an additional challenge in assessing whether a given genetic alteration reflects an essential pathway that can serve as a molecular target." (PMID 36335173, 2022).
tumor (continued). "To explain this connection, we hypothesized that tumor cells with a stem cell phenotype are less dependent on MET signaling, but in tumors lacking the stem cell factor network where SOX2 is included, signaling through MET may be more crucial for cancer progression." (PMID 34069138, 2021). "However, whether HER2 and MET are co-expressed has not yet been fully studied in Chinese GC patients, and whether the combination of HER2 and MET targeted therapies can synergistically inhibit tumor growth has not been well established." (PMID 34557411, 2021). "However, tumor VEGFA mRNA and MET did have a 2.5±2.67-fold and 3.02±2.16-fold increase in comparing to that in the normal tissue in the patients, while the expression of ERBB2 mRNA showed a slightly decrease in the tumor vs non-tumor tissue (0.93±0.69-fold change)." (PMID 34335943, 2021). "Using a primary culture derived from a HER2-non-amplified MET (N375S) heterozygous tongue SCC tumor (NCC-NPC7), we confirmed the increased susceptibility to HER2 inhibitors (lapatinib and afatinib), but not to crizotinib as compared to a HER2-non-amplified MET wild-type HNSCC cell line (SCC13)." (PMID 32214092, 2020). "IHC of xenograft tissues revealed inhibited MET and AXL activation; however, in vivo tumor cell proliferation or apoptosis was not affected by LY2801653 (data not shown), which was in accordance with our in vitro results, suggesting the antitumor mechanism might be related to tumor microenvironment." (PMID 34766112, 2020). "Furthermore, APC (p < 0.0001), ASXL1 (p < 0.0001), DNMT3B (p = 0.001), PARP4 (p = 0.002), MET (p = 0.01), TOP1 (p = 0.01), KDR (p = 0.01), SRC (p = 0.01), PAK1 (p = 0.015), ALK (p = 0.02), and MYC (p = 0.03) alterations were found to be more common in tumor samples from AO mCRC patients." (PMID 33194656, 2020). "Hiroya Takeuchi and coworkers reported that c-MET copy numbers in primary CRC of N1/N2-stage patients were significantly higher than the copy numbers in N0 cases (P < 0.03) and that overexpression of c-MET mRNA in primary CRC may be a predictor of tumor invasion and lymph node metastases." (PMID 31182111, 2019). "Unfortunately, our study reveals that MLN0128 alone or combined with PD901 treatment fails to induce robust apoptosis in vitro and in vivo, which could explain why the combination therapy was able to induce a stabilization -but not regression- of tumor development in AKT/c-MET mice." (PMID 31277283, 2019). "Moreover, tumor-excreted circ-PDE8A could be released into blood circulation by exosome transportation, acting as a ceRNA for miR-338 to regulate MACC1 and promote invasive metastasis through the MACC/MET/ERK or AKT pathways." (PMID 31277663, 2019). "Therefore, the HGF/c-MET feedback loop regulates tumor proliferation, invasion and migration and may be a novel target for growth factor-induced tumor growth." (PMID 30567565, 2018). "As MET and AXL are involved in resistance mechanisms, especially in NSCLC, inhibiting both simultaneously may target distinct resistant populations within the same tumor, or prevent the emergence of secondary mechanisms of resistance, and thus be highly beneficial for patients." (PMID 28251492, 2017). "However, the diverse compositions of the MET exon 14 splice sites and their variable locations in intronic regions require the examination of large and new sequences by high-throughput sequencing or genotyping technologies using formalin-fixed paraffin-embedded (FFPE) tumor samples." (PMID 28418914, 2017). "Thus, PIK3CA, NRAS, HRAS, PTEN, MET, and IDH2 R140Q mutations might be related to the metastasis process rather than primary tumor development." (PMID 29290998, 2017). "Moreover, tumor-synthesized VEGF is an important immunosuppressive cytokine for eluding immunosurveillant cells (e.g., NK cells, T cells, and so on), and MET and EGFR are also strong therapeutic target candidates in numerous cancers, including those of the lung and colorectum." (PMID 28388297, 2017).
tumor (continued). "An inverse relationship between Androgen Receptor (AR) and c-MET has been already demonstrated suggesting that a reduction of AR activity through androgen ablation may increase the expression of c-MET, directly contributing to androgen insensitivity and favoring tumor aggressiveness." (PMID 26887047, 2016). "Having found that CDK4 but not CDK6 could regulate MET and the phenotype of the cells, we next investigated the potential role of CDK6 in regulating cancer stemness in TNBC and its potential association with tumor progression and outcomes." (PMID 27759034, 2016). "Interestingly, two tumor-suppressive miRNAs, let-7 and miR-34, are the most common altered miRNAs in NSCLC tumor tissue The reduction in let-7 and miR-34 expression is relevant in the NSCLC oncogenic phenotype and is involved in the maintenance of oncogene addiction, via RAS, BCL2, MET or MYC." (PMID 26425674, 2015). "While preliminary data from patient subsets in randomized Phase II trials have shown that high MET protein expression as measured by IHC can differentiate patients who may benefit from MET pathway blockade, the success of MET IHC as a predictive biomarker has not been universal in all tumor types." (PMID 24930887, 2014). "Notably, MET aberrant function does not affect only the tumor cells, but may also exert a crucial impact on the tumor microenvironment, enabling tumor growth and systemic dissemination." (PMID 24378750, 2013). "Within our own human HCC dataset, we found little differences in terms of mouse and human overlapping down-regulated or up-regulated tumor to normal signatures no matter whether we used the whole HCC populations or the subpopulation with higher c-MET expression." (PMID 21949730, 2011). "If the VEGF165-NRP1-c-MET pathway is required for Mcl-1 expression and survival in PCa cells, it would be intriguing to evaluate whether targeting NRP1 could interrupt both NRP1-c-MET signaling in tumor cells (survival) and NRP1-VEGF-Rs signaling in endothelial cells (angiogenesis)." (PMID 20085644, 2010). "At higher doses, LY2801653 also affected tumors lacking MET/AXL expression by reducing angiogenesis and M2 macrophages in the tumor microenvironment." (PMID 41011010, 2025). "AS1411-SL1-2 and AS1411-SL1-3 showed no impact on the c-MET level in MCF 10A cells, underscoring the tumor selectivity of the AS1411-SL1 chimeras." (PMID 39744222, 2025). "In mouse xenograft models, a single dose of BYON3521 produced significant antitumor effects across various tumor types without MET amplification, achieving complete tumor regression in models with moderate c-MET expression." (PMID 39664377, 2024). "In PDX models of CRCs with moderate to high c-MET expression, a single dose of 1 mg/kg of TR1801-ADC resulted in complete tumor regression lasting for a period of 4 weeks, with no indications of tumor recurrence." (PMID 38269272, 2023). "In particular, MetMab significantly blocked HGF-dependent HCC tumor growth, but failed to inhibit growth of tumors with HGF-independent MET activation and overexpression." (PMID 37779207, 2023). "In vivo, HEPG2 xenograft models received bispecific or c-MET-CAR-T, and tumour burden was reduced (but not eliminated) in all mice by the end of the experiment (day 13) compared to control CAR." (PMID 35158772, 2022). "Another surprising and quite sobering example is Cabozantinib, an oral inhibitor of Tyrosine Kinases including MET and VEGFR2, two major drivers of malignant progression in several neoplasia, which did not guarantee an OS advantage in patients with PCa." (PMID 35222436, 2022). "One month after surgery, the three proteins, PLTP, MET and MFAP5, showed a decreasing trend, and when compared to patients without LUAD, the significance was no longer found, possibly indicating tumor removal." (PMID 36544145, 2022). "In ICC samples, the expression value of HBV-integrated genes, including MET, WNT2, BRD9, and TERT, in tumor seems to be higher than the paired non-tumor tissues." (PMID 36123506, 2022).
tumor (continued). "Overexpression of circMET was found to promote HCC development independent of MET function by inducing epithelial-to-mesenchymal transition (EMT) and enhancing the immunosuppressive tumor microenvironment." (PMID 35053615, 2022). "There were no studies of ANGPTL4, CRABP1, MET, and SEMA3A in Oncomine, but in UALCAN, they were frequently expressed in tumor group than normal tissues." (PMID 35833114, 2022). "Further targeted systemic therapy is limited to non-resectable advanced stage patients with tumor genetic alterations such as ALK (anaplastic lymphoma kinase), MET (Met proto-oncogene), RET Ret proto-oncogene), and ROS1 (c-ROS proto-oncogene 1)." (PMID 35448189, 2022). "Although we saw a minor FLCN-dependent effect of MET inhibitors in RPTEC, these effects were not reproducible in BHD tumor cell lines UOK257 and FLCN reconstituted UOK257-2." (PMID 35863698, 2022). "Pro-HGF is not a biological precursor because it does not activate MET (mesenchymal-epithelial transition) receptor, known as HGF receptor; however, the activation of two-chain HGF occurs in wounded tissue or the tumor microenvironment." (PMID 35630066, 2022). "CAF-mediated non-cell-autonomous adaptive resistance to MET- and EGFR-targeted therapies in lung cancers via a metabolic shift involving paracrine crosstalk between tumor cells under drug exposure and their surrounding CAFs has been reported." (PMID 35326670, 2022). "The hyaluronan synthase 2 myCAFs, but not type I collagen-expressing myCAFs, promoted tumor progression, while HGF-expressing iCAFs enhanced tumor growth via tumor-expressed MET, thereby directly linking CAFs to tumor cells." (PMID 35326670, 2022). "Our assays revealed that direct targeting of the PD-1/MET axis with a combination of drugs resulted in synergistic and direct PDAC cell cytotoxicity and inhibited tumor growth independent of the immune system." (PMID 35804822, 2022). "Moreover, it is unclear whether the apparently low detection rate of MET-GCNG/GA in MM using DNA/RNA-sequencing techniques could in fact reflect intratumor heterogeneity resulting in the presence of this MET alteration only in minor, difficult-to-detect MM cell populations within the tumor tissue." (PMID 34884673, 2021). "Immunofluorescence of FFPE sections derived from PDX tumours (GCRC1886 and GCRC1915) revealed that MET and FGFR1 are not mutually exclusive and that both RTKs are expressed in the same tumour cells." (PMID 33772015, 2021). "Of these, 17 tumor samples were MET-amplified and one patient was found to have a MET rearrangement by NGS, while two samples had no MET gene alteration." (PMID 34733418, 2021). "In addition, c-MET oncogene, which codes for the tyrosine kinase receptor of HGF, could promote invasion and the metastatic potential of different cancers, including BC, through promoting angiogenesis, proliferation, invasiveness, and survival of the tumor cells." (PMID 34577857, 2021). "Hence, the activation of Src may not be strictly c-MET-dependent in tumor hypoxia of GPCs." (PMID 33859738, 2021). "Patients with MET exon 14 skipping NSCLC typically have a poor prognosis and low tumour response rates with non-targeted therapies." (PMID 34037224, 2021). "Teliso‐v targets c‐Met–overexpressing tumor cells, irrespective of MET gene amplification status, resulting in blockade of both HGF‐dependent and HGF‐independent c‐Met signaling." (PMID 33675179, 2021). "Although MET gene copy number gain and protein overexpression were proved to drive CRC tumor malignant progression, MET gene fusions have not been noted in CRCs before." (PMID 34657620, 2021). "Of the 30 MET and HER2 amplifications, 10 were exclusively detected by ISH or IHC, and not detected by DNA NGS, mostly owing to low tumor cell percentage (<30%) and possibly tumor heterogeneity." (PMID 34849493, 2021).